AKT1 (AKT serine/threonine kinase 1)
Diseases named in the same sentence as AKT1 in open-access papers (continued):
Sharing a sentence is not in itself a finding about the gene and the disease.
breast cancer (continued). "Other studies have also found that Akt1 is the most important Akt isoform at inhibiting apoptosis induction in breast cancer and mouse myeloid cells." (PMID 32438621, 2020). "Pathway analysis also indicated that Prunella vulgaris L. exerts anti-breast cancer effects by inhibiting key targets in the estrogen pathway and ErbB pathways, such as AKT1, EGFR, and MYC." (PMID 32978480, 2020). "Because AKT1 is a known negative regulator of invasion in breast cancer cells, our findings suggest that EDNRB-442 activates AKT1 and thereby inhibits breast cancer invasion." (PMID 32201539, 2020). "For example, independent breast cancer studies have shown that AKT1 suppresses migration and metastasis and BCL3 inhibits apoptosis and tumor progression." (PMID 33371906, 2020). "It is astonishing that the majority of the studies on AKT1 have shown an inhibitory effect on the invasion and metastasis of breast cancer." (PMID 33291460, 2020). "In the luminal breast cancer cell line MCF-7,phosphatidylinositol-4,5-bisphosphate 3-kinase catalytic subunit alpha (PIK3CA) butnot AKT1 mutation increased sensitivity to MK22067." (PMID 33083527, 2020). "Infrequent mutations in CBFB, MAP3K4 and ZNF384 are enriched in Stage I, together with classic breast cancer gene AKT1." (PMID 33087126, 2020). "While AKT1 is pro-tumorigenic in lung cancer and ErbB2 positive breast cancer, its silencing is pro-tumorigenic in prostate and other types of breast cancer." (PMID 32764385, 2020). "AKT genetic aberrations that increase AKT activity have been detected in multiple malignancies and are especially common in breast cancer, where AKT3 amplification and AKT1 E17K oncogenic mutation have been reported in up to 24% and 1–8% of cases respectively." (PMID 32630372, 2020). "Ablation of single AKT isoforms in oncogene-driven mouse models of breast cancer has revealed more complex roles for AKT1 and AKT2 in regulating mammary tumour progression." (PMID 33276499, 2020). "Effectively separating these effects, either inhibition of PI3 kinase or knock-down of downstream AKT1 were later shown to impair the survival of tumor initiating supposed breast carcinoma stem cells." (PMID 31477842, 2020). "In line with our observations, the expression of Akt1 and 2 were found to be different in early and late stages of breast cancer." (PMID 31252679, 2019). "AKT1 expression was found to be lower in breast cancer than in corresponding normal mammary tissue, perhaps pointing to the anti-migratory effect of AKT1." (PMID 31752925, 2019). "Many candidate genes emerged to be related to this breast cancer subtype, such as AKT1, AKT3, INPP4B, and EGFR." (PMID 30630526, 2019). "Following this, Akt1 was identified as a negative regulator of breast cancer metastasis in vivo via proteolytic degradation of twist-1, a transcriptional factor that induces EMT." (PMID 31360736, 2019). "AKT1 and AKT3 are associated with breast cancer invasion, and PTEN-deficient tumors depend on AKT2 for maintenance and survival." (PMID 30837881, 2019). "AKT1 blocks migration and invasion of breast cancer cells through an inactivating phosphorylation of GSK3 and therefore a HDM2-mediated proteasomal degradation of the pro-migratory transcription factor NFAT1." (PMID 31752925, 2019).
breast cancer (continued). "With regard to breast cancer, AKT1 plays a crucial role for proliferation and tumor growth in vivo by regulating the cell cycle and attenuates the influence of cell cycle inhibitors." (PMID 31752925, 2019). "Recently, in breast cancer, AKT1 has been shown to be involved in the local tumor growth while AKT2 in the distant tumor dissemination." (PMID 31781306, 2019). "AKT1 is responsible for proliferation and survival of breast cancer cells, whereas it has an anti-metastatic effect." (PMID 31752925, 2019). "In contrast to the general findings in breast cancer, AKT1 knockdown in mouse embryo fibroblasts decreases migration and invasion, whereas AKT2 has an anti-migratory and anti-invasive effect." (PMID 31752925, 2019). "The E17K AKT1 mutation also occurs in DCIS, suggesting the mutation is an early event in breast cancer." (PMID 31752925, 2019). "BAY 1125976 is a highly potent and oral specific allosteric inhibitor of AKT1/2 and demonstrated antitumor activity in several preclinical cancer models, including breast cancer." (PMID 31835495, 2019). "Comparison of the AKT1 E17K mutation and the mutation of PIK3CA displays enhanced AKT1 activity in the AKT1 mutation, but elevated activity of AKT1 and AKT2 in the PIK3CA mutated breast cancer cells." (PMID 31752925, 2019). "Poorly differentiated mammary tumors have low levels of AKT1 and AKT2, proposing a pivotal role of both isoforms in differentiation of breast tumors." (PMID 31752925, 2019). "On the downside AKT1 decreases migration of breast cancer cells, for instance by regulating TSC2, palladin and EMT-proteins." (PMID 31752925, 2019). "A cross-talk between STAT5 (activated by JAK2) and Akt1 has also been reported that is essential for progression of breast cancer." (PMID 31681603, 2019). "MiR-409-3p is an additional AKT1-specific upstream regulator that suppresses the total AKT1 protein amount in breast cancer cells." (PMID 31752925, 2019). "In this study, siRNA-mediated Akt1 deletion promoted breast cancer cell invasion via the human homolog of the E3 ubiquitin ligase (HDM2)-mediated ubiquitination and degradation of the nuclear factor of activated T-cells (NFAT)." (PMID 31360736, 2019). "In combination with the fact that GSK3 is regulated by AKT1 in breast cancer regulating the migration, an isoform specific modification of metabolism as a hallmark of cancer can also be assumed in breast cancer." (PMID 31752925, 2019). "The dysregulation of the PI3K/AKT pathway has been demonstrated in different solid tumors including breast cancer, and it has been suggested that this dysregulation is associated with the increased mutations in pathway genes PIK3CA and AKT1." (PMID 30682127, 2019). "Within comprehensive molecular profiling studies of breast cancer tissue, the AKT1E17K mutation was identified as a probable oncogenic driver in patients, indicating that the inhibition of AKT1 presents a novel and specific drug target in this disease." (PMID 31835495, 2019). "In metastatic HER2-positive breast cancer a high AKT1 level was found in 12.2% of the samples and high AKT2 levels occurred in 35.1%." (PMID 31752925, 2019). "In breast cancer, AKT1 had been demonstrated to suppress while AKT2 promotes migration and invasion." (PMID 31470874, 2019). "A high AKT1 activation was observed in 19.9% of all breast cancer probes and 45% of human ductal breast cancer, the latter mainly due to high PI3K activity." (PMID 31752925, 2019). "Roughly summarized, AKT1 is important for breast cancer initiation and growth of the primary tumor, whereas AKT2 plays a pivotal role in progression of breast cancer by formation of metastases." (PMID 31752925, 2019).
breast cancer (continued). "Surprisingly, the AKT1 knockdown breast cancer cells in this study showed a higher invasiveness despite lower metastasis." (PMID 31752925, 2019). "Contrary, another study detected a transforming ability of AKT1 in breast cancer through enhanced proliferation and suppressed apoptosis." (PMID 31752925, 2019). "AKT1 activity is often increased in breast cancer and its activation is essential to protect cells against death insults." (PMID 30646605, 2019). "This is supported by its co-expression with antiapoptotic proteins; BCl2, AKT1 and NF Kappa-B in residual breast carcinoma cells and very low proliferating index and apoptotic bodies in residual tumors." (PMID 30744593, 2019). "There was significant co-expression of TFF3 with AKT1 (p = 0.0365), BCl2 (p = 0.0152), and NF Kappa-B (p = 0.0243) in breast carcinoma cases with residual carcinoma following neoadjuvant therapy which support the role of TFF3 in chemoresistance." (PMID 30744593, 2019). "There was significant co-expression of TFF3 and AKT1 in breast carcinoma cases treated with neoadjuvant therapy (p = 0.0365) which supports the anti-apoptotic role of TFF3." (PMID 30744593, 2019). "On the same track we also have shown a significant co-localization of TFF3 and p- AKT-1 in breast carcinoma cells in residual tumors suggesting a possible association between TFF3 and AKT-1 in incomplete pathological response group." (PMID 30744593, 2019). "In the case of breast cancer cells, knockdown of Akt1 induced an elevated expression of β-catenin total protein." (PMID 30445978, 2018). "In contrast to Akt1, which accelerates the induction of mammary tumours in transgenic mice, Akt2 can promote metastasis of tumour cells without affecting the latency of tumour development in certain systems." (PMID 29890731, 2018). "The pathway that is described in these TIC tumour cells was different from those that were described for Akt1 (initially only in some breast cancer cells)." (PMID 29518912, 2018). "Together, these results indicated that β-catenin nuclear accumulation contributes to Akt1 inhibition-mediated breast cancer cell invasion." (PMID 30445978, 2018). "For example, preclinical data suggested that AKT2 promotes metastasis in ovarian and breast cancer cell models while AKT1 was proposed to inhibit the migration and metastasis of breast cancers." (PMID 29506489, 2018). "Here we demonstrate that the alternative action of AKT1 on invasive properties of breast cancers can be extended to head and neck carcinomas, which exhibit constitutive activation of the PI3K/AKT pathway." (PMID 29506489, 2018). "Further, E2 is able to induce BCL-2 and CCND1 in breast cancer cells and they are downstream from AKT1." (PMID 29416771, 2018). "Recently, Li CW have found inhibition of Akt1 using MK-2206 induced epithelial-to-mesenchymal transition through blocking Twist1 degradation in breast cancer." (PMID 30445978, 2018). "For MCF-7 breast cancer cells, NutramilTM Complex reduced significantly the expression of pro-survival AKT1 down to 82% of UC (P≤0.05)." (PMID 29444163, 2018). "Together, these data indicated that Akt1 inhibition led to increased activation of ERK signaling in breast cancer cells, resulting in β-catenin nuclear accumulation and cancer cell invasion." (PMID 30445978, 2018). "In breast cancer, Akt1 appears to play a fundamental role in the propagation of such tumours, whereas ablation of Akt2 inhibits apoptosis and delays tumour involution." (PMID 29518912, 2018). "Studies from the Brugge laboratory documented that Akt1 inhibits breast cancer cell motility through the suppression of ERK activation." (PMID 30445978, 2018).
breast cancer (continued). "Knockdown of Akt1 stimulated β-catenin nuclear accumulation, resulting in breast cancer cell invasion." (PMID 30445978, 2018). "Accumulating reports suggest that overexpression of Akt1 in breast cancer cells blocks cell motility and invasion." (PMID 30445978, 2018). "For instance, Akt1 is essential for the propagation of breast cancer, whereas ablation of Akt2 inhibits apoptosis and delays tumour involution." (PMID 29890731, 2018). "In different breast cancer models, Akt1 appears to play a fundamental role in the propagation of such tumours by enhancing not only proliferation and survival, but also cell migration." (PMID 29890731, 2018). "As expected, the protein expression of Akt1 was downregulated in these breast cancer cells after treated with 20 nM Akt1 siRNA for 24 h." (PMID 30445978, 2018). "For example, Akt1 activation accelerates cell proliferation but inhibits cell motility and invasion in breast cancer cells, whereas Akt1 inhibition promotes Epithelial-to-Mesenchymal Transition in breast cancer." (PMID 30445978, 2018). "The reduction of Akt1 in these breast cancer cells induced cell death in which a MET transition preceded apoptosis." (PMID 29518912, 2018). "Collectively, these data demonstrate that knockdown of Akt1 prolonged EGFR activation through inactivating PIKfyve in breast cancer cells." (PMID 30445978, 2018). "Of course, the unexpected effects of Akt1 suppression on cancer metastasis are reported not only in breast cancer but also in prostate, liver, head & neck and non-small cell lung cancer cells (NSCLC)." (PMID 30445978, 2018). "Collectively, these results suggested the activation of EGFR mediates β-catenin nuclear accumulation in Akt1-impaired breast cancer cells." (PMID 30445978, 2018). "For example, AKT1 has been demonstrated to suppress while AKT2 promotes breast cancer cell migration and invasion in vitro." (PMID 30012111, 2018). "EGFR-mediated β-catenin nuclear accumulation is critical for Akt1 inhibition-induced breast cancer metastasis." (PMID 30445978, 2018). "In support of this report, we did find more co-localization of EGFR with the early endosomes marker EEA.1 in Akt1-impaired breast cancer cells." (PMID 30445978, 2018). "Further, using selective Akt inhibitor, perifosine or overexpression of Akt1 demonstrates that it regulates breast cancer cell migration, angiogenesis and induces apoptosis through PI3K/Akt pathway." (PMID 29310608, 2018). "The Interleukin 8 (IL-8) gene and its receptor, CXCR2, have been described as markers of tumor progression, acting through repression of the AKT1 gene on breast cancer cell lines." (PMID 30173296, 2018). "Our results provided the evidence that EGFR-mediated β-catenin nuclear accumulation is critical for the Akt1 inhibition-induced breast cancer metastasis." (PMID 30445978, 2018). "As a proof of concept, a previous study showed that inhibition of caveolin-1 signalling by siRNA or caveolin scaffolding peptide in inflammatory breast cancer cells resulted in a reduction in invasive potential in an Akt1-dependent manner." (PMID 29331414, 2018).
breast cancer (continued). "MK-2206 is a pan-Akt inhibitor, which has potential to induce EMT in breast cancer cells at a low dosage of 0.2 μM through inhibition of Akt1." (PMID 30445978, 2018). "In contrast to Akt1, which accelerates the induction of mammary tumours in transgenic mice, Akt2 can promote the metastasis of tumour cells without affecting the latency of tumour development in certain systems." (PMID 29518912, 2018). "Western blotting, immunofluorescence, luciferase assay, real time PCR, ELISA and Matrigel invasion assay were used to investigate how Akt1 inhibition promotes breast cancer cell invasion in vitro." (PMID 30445978, 2018). "Our data showed a prominent role of Akt1, and to a lesser extent, Akt2, in such processes in TICs derived from breast cancer cells." (PMID 29518912, 2018). "To the best of our knowledge, we disclosed for the first time that EGFR-mediated β-catenin nuclear accumulation is critical for the Akt1 inhibition-induced breast cancer metastasis." (PMID 30445978, 2018). "Surprisingly, breast cancer cells (BT474) treated with Akti-1/2 (1 μM) showed a rebound effect in Akt1 phosphorylation status following Akti-1/2 treatment." (PMID 30205513, 2018). "β-catenin nuclear accumulation induced by Akt1 inhibition depended on the prolonged activation of EGFR signaling pathway in breast cancer cells." (PMID 30445978, 2018). "AKT1 localizes to the cytoplasm in a number of human breast cancer cell lines, whereas AKT2 is present in mitochondria and the cytoplasm and AKT3 exhibits a nuclear and nuclear membrane distribution." (PMID 28082369, 2017). "Previous publication has demonstrated that constitutively activated AKT1 expression inhibited the basal-like breast cancer cell line MDA-MB231 cells proliferation." (PMID 28301567, 2017). "We analyzed the AKT1 methylation and expression level according to the clinicopathological characteristics of the breast cancer patients." (PMID 28301567, 2017). "In the comparison of AKT1 methylation and expression between basal-like tumor and other subtypes, it revealed significant lower AKT1 expression (P = 0.0328) in basal-like breast cancer than other subtypes." (PMID 28301567, 2017). "Very interestingly, a recent report demonstrated that AKT1 can switch from being a promoter to being a blocker of cell migration and metastasis in breast cancer, as a result of ablation of inositol polyphosphate 5-phosphatase PIPP13." (PMID 28765579, 2017). "By using PCR target sequence enrichment and next-generation sequencing technology, we sequenced AKT1 promoter region in pairs of breast tumor and normal tissues from 95 unselected Chinese breast cancer patients." (PMID 28301567, 2017). "In breast cancer, in particular, SF3B1 mutations were significantly associated with ER-positive disease, AKT1 mutations, and distinct copy number alterations." (PMID 28198434, 2017). "Our observation suggested that AKT1 expression aberrations likely play distinct role in the pathogenesis of different breast cancer subtypes." (PMID 28301567, 2017). "A subset of breast cancer specimens was found to only contain AKT1 as a driver alteration, although AKT1-mutants were also often found to contain mutations in other driver genes." (PMID 28589855, 2017). "In breast cancer cell lines, AKT1 suppresses cell migration by inducing degradation of NFAT through E3 ubiquitin ligase HDM210." (PMID 28765579, 2017).